CDCP1 (CUB domain containing protein 1)
Diseases named in the same sentence as CDCP1 in open-access papers (continued):
Sharing a sentence is not in itself a finding about the gene and the disease.
melanoma (8 papers, 2014 to 2025). A malignant, usually aggressive tumor composed of atypical, neoplastic melanocytes. "Since OXPHOS/metastasis pathway has been reported in other types of cancer besides TNBC, including pancreatic, ovarian, melanoma and prostate cancers, the CDCP1/mitochondrial Src pathway needs to be further investigated in these cancer cell contexts." (PMID 40908298, 2025). "CDCP1 and/or Src signaling has been reported to potentiate metastasis in multiple mouse models of cancer including breast, prostate, melanoma and colorectal cancers." (PMID 40908298, 2025). "CDCP1 expression has been reported in several cancers, including tumors of the colon, prostate, kidney, lung and pancreas in particular, and in melanomas." (PMID 25876044, 2015). "CDCP1 was reported to be phosphorylated by Src-family protein kinases (SFKs) and to activate SFKs in metastasizing melanoma and tumor cell lines." (PMID 25275584, 2014). "A phosphoproteomic analysis of melanoma tumor cells and cell lines showed that metastatic cells expressed larger amounts of CDCP1 and that the forced expression of CDCP1 in melanoma cell lines led to the activation of SRC and to an increase in metastatic potential." (PMID 25876044, 2015). "It will be important to validate our findings in other CDCP1/Src-driven cancer types that are also reliant on OXPHOS for disease progression such as prostate, melanoma, and colorectal, amongst others." (PMID 40908298, 2025).
Autoimmunity (6 papers, 2020 to 2025). The occurrence of an immune reaction against the organism's own cells or tissues. "CDCP1 is believed to modulate immune responses upon T cell activation and has been implicated in inflammatory responses and autoimmunity." (PMID 35967338, 2022). "It is therefore interesting that aberrant CDCP1-singaling has been previously associated with autoimmunity and inflammation." (PMID 32983115, 2020). "CDCP1 is a widely expressed transmembrane glycoprotein that acts as a ligand for T cell-expressed Cluster of Differentiation 6 (CD6),and is implicated in autoimmune conditions." (PMID 38762535, 2024).
gastric cancer (5 papers, 2012 to 2025). A primary or metastatic malignant neoplasm involving the stomach. "In contrast, engineered over-expression of CDCP1 in the gastric cancer cell lines HSC59 and HSC60 increased cell migration." (PMID 25301083, 2014). "In pancreatic and gastric cancer cells, CDCP1 phosphorylation and signalling appeared to be required for CDCP1-mediated migration." (PMID 25301083, 2014).
rheumatoid arthritis (5 papers, 2022 to 2026). A chronic, systemic autoimmune disorder characterized by inflammation in the synovial membranes and articular surfaces. "Rheumatoid arthritis: Six inflammatory factors, including Neurturin, Interleukin-6, Programmed cell death 1 ligand 1, CUB domain-containing protein 1, C-C motif chemokine 4, and CD40L receptor, are significantly associated with RA." (PMID 41399369, 2026). "CUB domain-containing protein 1 is a ligand for CD6, which is a type I transmembrane glycoprotein expressed by T-lymphocytes and has been described to be involved in the pathophysiology of autoimmune-mediated diseases as multiple sclerosis and rheumatoid arthritis." (PMID 41154673, 2025).
cervical cancer (4 papers, 2022 to 2025). A primary or metastatic malignant neoplasm involving the cervix. "Across all normal and malignant cohorts, highest levels of CDCP1 mRNA were observed in esophageal carcinoma, the normal head and neck region, head and neck squamous cell carcinoma, cervical and endo-cervical cancer, and PDAC." (PMID 36276654, 2022).
dementia (4 papers, 2022 to 2025). Loss of intellectual abilities interfering with an individual's social and occupational functions. "Higher levels of TNFB and CDCP1 were associated with higher risks of incident all‐cause and AD dementia." (PMID 37584418, 2023). "Meanwhile, CDCP1 can effectively distinguish some dementia cases from cognitively normal elderly people." (PMID 40746641, 2025). "We found several proteins associated with cognitive function and risks for incident dementia: IL10, LIF‐R, TWEAK, CCL19, IL‐17C, MCP‐4, TGF‐alpha, TNFB, CDCP1, etc." (PMID 37584418, 2023). "This study identified two inflammatory biomarkers associated with incident dementia (TNFB and CDCP1) and one (TNFB) was also associated with incident AD dementia in the full sample and among ε4 carriers." (PMID 37584418, 2023). "The increased dementia risk in individuals with high levels of plasma SVEP1, HE4, CDCP1, SIGLEC‐7, MARCKSL1, CRDL1, or RNAS6 is a novel finding." (PMID 34338426, 2022). "In the ε3 stratum, TNFB, CDCP1, and CX3CL1 were significantly associated with incident dementia." (PMID 37584418, 2023). "Higher levels of TNFB and CDCP1 remained significantly associated with higher risks of incident dementia, with HR of 1.64 per unit increase in TNFB level (95% CI = (1.33, 2.03), FDR <0.001) and HR of 1.68 per unit increase in CDCP1 level (95% CI = (1.28, 2.21), FDR = 0.007)." (PMID 37584418, 2023). "Higher levels of TNFB and CDCP1 were associated with higher risks of incident dementia, with a hazard ratio (HR) of 1.65 per unit increment in TNFB level (95% CI = (1.33, 2.03), FDR < 0.001) and HR of 1.66 per unit increment in CDCP1 level (95% CI = (1.28, 2.16), FDR = 0.005)." (PMID 37584418, 2023). "Higher plasma levels of CDCP1, OPG, and HGF have been shown to accurately discriminate dementia cases from cognitively normal older adults." (PMID 36737481, 2023). "In addition to demonstrating their relationship to inflammatory diet and incident cognitive impairment/dementia, we identified OPG, HGF, NFATC3, CDCP1, and ITGA11 as differentially expressed at the RNA level in brain tissue of deceased individuals with pathologically defined AD." (PMID 36737481, 2023).
glioma (4 papers, 2016 to 2023). A benign or malignant brain and spinal cord tumor that arises from glial cells (astrocytes, oligodendrocytes, ependymal cells). "CDCP1 expression was reduced in glioma tissues and was associated with the prognosis of glioma." (PMID 33260155, 2020). "Further, correlation analysis revealed a significant association between ADAM9 and CDCP1 in glioma." (PMID 33260155, 2020). "The median OS times of glioma patients with high and low expression of CDCP1 were 18 and 41 months, respectively, in the CGGA database (p< 0.0001)." (PMID 35410293, 2022). "To further confirm these results, we examined the CDCP1 expression level in glioma tissues (grade II, n = 35; grade III, n = 42; and grade IV, n = 55) and normal brain tissues (n = 35) by immunohistochemistry." (PMID 35410293, 2022). "The median OS times of glioma patients with high and low expression of CDCP1 were 13 and 20 months, respectively, in the TCGA database (p< 0.0001)." (PMID 35410293, 2022). "We showed that CDCP1 plays an important role in glioma patients by examining data from the TCGA, CGGA and GEO databases." (PMID 35410293, 2022). "In this study, data obtained from public datasets (TCGA, CGGA, and GEO) and specimens collected from resected glioma samples revealed that CDCP1 expression was higher in glioma tissue than in normal brain tissue." (PMID 35410293, 2022). "Our study is the first to report that CDCP1 is a potential biomarker of the malignant phenotype of glioma and confirmed that the expression of CDCP1 increases with the grade of glioma." (PMID 35410293, 2022). "We established a risk model (which considered the expression of CDCP1 combined with CD44 and ITGAM) and verified that it can be used to predict prognosis in glioma/GBM." (PMID 35410293, 2022). "By combining CDCP1, CD44 and ITGAM, a prognostic risk model was established and validated to predict 1-year, 3-year, and 5-year survival in glioma patients." (PMID 35410293, 2022). "Our previous studies suggested that the expression of CDCP1 in MES-GBM was significantly higher than that in PN-GBM, but the role and mechanism of CDCP1 in glioma are still unclear." (PMID 35410293, 2022). "The contribution of the ADAM9-CDCP1-tPA axis and the cleavable form of CDCP1 in glioma requires future exploration." (PMID 33260155, 2020). "Then, we observed the regulation of glioma cell proliferation and migration by ectopic expression of CDCP1." (PMID 33260155, 2020). "To clarify the role of CDCP1 in the progression of glioma, we also analyzed the potential clinical implications of CDCP1 using data from the TCGA database." (PMID 33260155, 2020). "The emerging roles of CDCP1 in various tumors led us to evaluate the potential possibility of CDCP1 participating in glioma and miR-1272-induced effects." (PMID 33260155, 2020). "Results derived from clinical samples and online databases confirmed correlations between the expression of ADAM9 and CDCP1 and both the severity and prognosis of glioma." (PMID 33260155, 2020). "Here, we detected the expression of ADAM9 and CDCP1 in glioma cells transfected with miR-1272 mimic or ADAM9 overexpression plasmid." (PMID 33260155, 2020). "The risk model (considering CDCP1 combined with CD44 and ITGAM expression) could represent a tool for predicting survival and prognosis in glioma patients." (PMID 35410293, 2022). "Based on these findings and the findings of the biological/functional analysis of CDCP1 in glioma, we hypothesize that CDCP1 can significantly promote the migration and invasion of glioma cells." (PMID 35410293, 2022). "Moreover, high expression of CDCP1 correlated with a poor prognosis of glioma, as revealed by survival analysis." (PMID 35410293, 2022). "We also found that CDCP1 serves as a potential downstream molecule of miR-1272/ADAM9 in glioma." (PMID 33260155, 2020). "The results suggested that the expression of CDCP1 was upregulated in glioma tissues." (PMID 33260155, 2020).
glioma (continued). "Further, analysis of overall and disease-free survival among glioma patients revealed that glioma patients with higher expression of CDCP1 had a decreased survival time compared to glioma patients with lower expression of CDCP1." (PMID 33260155, 2020). "Furthermore, CDCP1 served as a potential downstream molecule of miR-1272/ADAM9 signaling in glioma and promoted the proliferation and migration of glioma." (PMID 33260155, 2020). "Further study of the miR-1272/ADAM9/CDCP1 axis may provide us with a potential mechanism of glioma progression." (PMID 33260155, 2020). "Then, miR-1272-ADAM9 signaling can regulate the expression of CDCP1, and CDCP1 acts as an oncogene in glioma, thus suggesting that CDCP1 may participate in glioma progression and the miR-1272-ADAM9 signaling pathway." (PMID 33260155, 2020). "The miR-1272/ADAM9/CDCP1 pathway may serve as a potential candidate pathway for the prevention of glioma." (PMID 33260155, 2020). "There is extensive evidence suggesting that one of the human-specific genes CDCP1, collaboratively regulated by H3K4me3HP and TF, may act as a novel regulator and promote the proliferation and migration of glioma, which is a primary, malignant, and aggressive brain tumor in adults." (PMID 37226244, 2023). "Moreover, targeting the miR-1272/ADAM9/CDCP1 pathway may serve as a potential therapeutic strategy for glioma treatment." (PMID 33260155, 2020). "However, the functional role of CDCP1 in glioma progression remains elusive." (PMID 33260155, 2020). "In conclusion, these results suggest that miR-1272 and CDCP1 may act as novel regulators in glioma." (PMID 33260155, 2020). "However, the function and potential molecular mechanism of CDCP1 in glioma remain unclear." (PMID 35410293, 2022). "The mRNA expression data of CDCP1 in glioma were collected from the TCGA, CGGA and GEO databases, and in vitro experiments verified CDCP1 expression in glioma tissue samples." (PMID 35410293, 2022). "Ultimately, we speculate that CDCP1, CD44 and ITGAM can be used to better diagnose glioma and predict the prognosis of glioma patients." (PMID 35410293, 2022). "In order to examine the potential role of CDCP1 in the tumorigenesis of glioma, CDCP1-overexpressing plasmid and its negative control were used to transfect SHG44 cells." (PMID 33260155, 2020). "However, the potential roles of CDCP1 and the ADAM9-CDCP1 pathway as a whole in the progression of glioma have not yet been characterized." (PMID 33260155, 2020).
non-small cell lung carcinoma (4 papers, 2015 to 2022). A group of at least three distinct histological types of lung cancer, including non-small cell squamous cell carcinoma, adenocarcinoma, and large cell carcinoma. "Together, this study suggests that AXL/SFK/AKT and CDCP1/SFK/AKT signaling pathways play some roles in acquired osimertinib resistance of non-small cell lung cancer." (PMID 35643725, 2022). "For example, mutations in the most frequently activated oncogenes, the Ras gene family, activate RAF/MEK/ERK which robustly induce CDCP1 mRNA and protein expression in non-small cell lung cancer (NSCLC) cells." (PMID 26973855, 2016). "An anti-CUB domain containing protein 1 (CDCP1) antibody was tested for tumour growth inhibition in a patient-derived xenograft model, generated from a stage-IV non-small cell lung carcinoma, with and without cisplatin." (PMID 26227951, 2015).
renal carcinoma (4 papers, 2016 to 2024). A carcinoma arising from the epithelium of the renal parenchyma or the renal pelvis. "This HGF-independent CDCP1-Met interaction was also observed in the renal cancer cell lines, A498 and ACHN, in which endogenous CDCP1 and Met are up-regulated." (PMID 33574034, 2021). "Out of the unique set of genes detected by BNNPT, a few were reported to be relevant to renal cancer or disease: CDCP1, GSTT1, E2F3, MAPK1, SALL4, SIRT1, ADAMTS13, Gfrα1, ASPH, MIR17HG, APOE, BMP4, RCOR1, NUMB and SEC63." (PMID 28986523, 2017).
acute myeloid leukemia (3 papers, 2020 to 2025). Acute myeloid leukemia (AML) is a group of neoplasms arising from precursor cells committed to the myeloid cell-line differentiation. "Fbxl4 induces the ubiquitination and degradation of CUB-domain-containing protein 1 (CDCP1), a transmembrane adaptor protein, identified as a malignant prognostic marker in several types of cancers, such as acute myeloid leukemia." (PMID 33114139, 2020).
chronic myeloid leukemia (3 papers, 2016 to 2021). "A recent study demonstrated that CDCP1 is increased ∼9 fold in chronic myeloid leukemia cells that are resistant to the selective Bcr-Abl kinase inhibitor nilotinib, and that silencing of CDCP1 markedly improved responses to nilotinib." (PMID 26973855, 2016).
clear cell ovarian cancer (3 papers, 2020 to 2025). "CDCP1 is a critical mediator of ovarian clear cell carcinoma progression, promoting spheroid formation, migration, and chemoresistance." (PMID 40892739, 2025). "CUB-domain containing protein 1 (CDCP1) is a cell-surface protein and has been identified to be overexpressed in multiple tumors including clear cell ovarian cancer." (PMID 32742495, 2020).
diabetes (3 papers, 2021 to 2025). "The importance of fatty liver was particularly striking among the top 30 diabetes-associated proteins (e.g. HGF, IGSF3, IL1RA, ALDH1A1, HNMT, ERBB2 and CDCP1)." (PMID 33279861, 2021). "We also found that diabetes was related to increased expression of nine proteins, IL-18R1, CCL11, CDCP1, OPG, HGF, TGF-α, CCL20, IL-6 and FGF-21." (PMID 34385358, 2021). "This study demonstrates positive associations of CDCP-1, FGF-21, IL-8, IL-18, eotaxin/CCL11, MMP-10, TNFRSF9, CCL25 and IL-10RB with depressive symptoms in people with diabetes without interaction with diabetes type." (PMID 39799156, 2025). "Nine biomarkers were positively associated with depressive symptoms in the total sample (CCL11/eotaxin, CCL25, CDCP1, FGF-21, IL-8, IL-10RB, IL-18, MMP-10, TNFRSF9; all p < 0.05) without interaction by diabetes type." (PMID 39799156, 2025).
endothelial dysfunction (3 papers, 2022 to 2025). In vascular diseases, endothelial dysfunction is a systemic pathological state of the endothelium (the inner lining of blood vessels) and can be broadly defined as an imbalance between vasodilating and vasoconstricting substances produced by (or acting on) the endothelium. "Key proteins, elevated in severe cases, including SYND1, S100A12, HGF and CDCP1, reflect processes such as endothelial dysfunction, neutrophil activation, tissue remodeling and systemic inflammation." (PMID 40429886, 2025). "Notably, IL-6 and CUB domain-containing protein 1 (CDCP-1) correlated with both endothelial dysfunction and the presence of plaques, whereas paraoxonase 3 (PON-3) showed protective, anti-atherogenic properties." (PMID 41427121, 2025).
leukemia (3 papers, 2020 to 2022). A malignant (clonal) hematologic disorder, involving hematopoietic stem cells and characterized by the presence of primitive or atypical myeloid or lymphoid cells in the bone marrow and the blood. "The authors suggest that CDCP1 could be used as independent marker for the diagnosis of leukemia, concluding that it appear to characterize immature erythroid and B lymphoid precursor cell subset." (PMID 33925480, 2021).
multiple sclerosis (3 papers, 2020 to 2025). A progressive autoimmune disorder affecting the central nervous system resulting in demyelination. "In an animal model for multiple sclerosis, knock-out of Cdcp1 led to improved clinical scores and reduced infiltration of CD4+ T cells producing IFN-γ and IL-17." (PMID 32983115, 2020). "In particular, people with multiple sclerosis on natalizumab had lower CD6, CDCP1, CXCL13, CXCL9, NfL, TNFRSF10a, TNFSF13B and VCAN (P < 0.036)." (PMID 37361716, 2023).
pancreatic ductal adenocarcinoma (3 papers, 2018 to 2026). An infiltrating adenocarcinoma that arises from the epithelial cells of the pancreas. "CUB domain-containing protein 1 (CDCP1) is implicated in pancreatic ductal adenocarcinoma (PDAC) prognosis, but its relationship to the tumor microenvironment (TME) and oncogenic signaling remains incompletely defined." (PMID 41488282, 2026). "(a) Profiling of a panel of pancreatic ductal adenocarcinoma cells by flow cytometry demonstrates that CDCP1 is highly expressed on PDAC cells." (PMID 29359686, 2018). "In this study, we investigated the relevance of targeting CDCP1 in the context of pancreatic ductal adenocarcinoma (PDAC) and assess the impact of CDCP1 proteolysis on the effectiveness of CDCP1 targeting agents." (PMID 32226543, 2020).
serous ovarian cancer (3 papers, 2020 to 2022). "Recent oncology studies revealed that targeting CDCP1 reduced migration and tumor burden in high-grade serous ovarian cancer." (PMID 35410293, 2022).
type 1 diabetes (3 papers, 2025). "Four biomarkers (CDCP1, IL-15RA, MIP-1α, PD-L1) showed inverse associations with CES-D changes in people with type 1 diabetes and positive associations with CES-D changes in people with type 2 diabetes." (PMID 40624224, 2025).
type 2 diabetes (3 papers, 2021 to 2025). "One of these proteins was CDCP1, the biomarker with the highest effect size in type 2 diabetes." (PMID 40624224, 2025).
Alzheimer disease (2 papers, 2024 to 2025). A progressive, neurodegenerative disease characterized by loss of function and death of nerve cells in several areas of the brain leading to loss of cognitive function such as memory and language. "CDCP1 has been found to be associated with a higher risk of all-cause dementia and Alzheimer’s disease, but associations with other neurological or psychiatric conditions have not been reported." (PMID 40624224, 2025). "Inverse variance weighted (IVW) MR analyses were performed to assess the effects of genetically predicted CA14, CDCP1, and MOG levels on cognitive function, structural brain phenotypes, and Alzheimer’s disease, and stroke." (PMID 38762535, 2024).